MYH7 (myosin heavy chain 7)
Diseases named in the same sentence as MYH7 in open-access papers (continued):
Sharing a sentence is not in itself a finding about the gene and the disease.
familial restrictive cardiomyopathy (1 paper, 2019). An instance of restrictive cardiomyopathy that is caused by an inherited modification of the individual's genome. "We discuss the case of a 43-year-old patient diagnosed with familial restrictive cardiomyopathy with positive genetic tests for mutations of MYH7 gene and ABCC9 gene, who was first hospitalized in 2011 for palpitations." (PMID 32309617, 2019). "Here, we describe the case of a 43-year-old patient diagnosed with familial restrictive cardiomyopathy, with mutations in MYH7 and ABCC9 genes." (PMID 32309617, 2019). "Most common genetic defects identified in familial restrictive cardiomyopathy are TNNI3 (one of the major causes of this condition), TNNT2, MYH7, ACTC1, TPM1, MYL3, MYL2." (PMID 32309617, 2019).
head and neck squamous cell carcinoma (1 paper, 2025). A squamous cell carcinoma that arises from any of the following anatomic sites: lip and oral cavity, nasal cavity, paranasal sinuses, pharynx, larynx, and salivary glands. "Similar findings in a previous study revealed that downregulated MYH7 is a biomarker for the poor prognosis of head and neck squamous cell carcinoma (HNSCC), and that MYH7 promotes CD4+ T cell activation in cancer." (PMID 40709170, 2025).
hypoplastic left heart syndrome (1 paper, 2024). Hypoplastic left heart syndrome (HLHS) refers to the abnormal development of the left-sided cardiac structures, resulting in obstruction to blood flow from the left ventricular outflow tract. "MYH7 (Myosin Heavy Chain 7, 160760), as the gene signature we predicted together with its homolog, has been identified from a genetic analysis of HF-hypoplastic left heart syndrome, revealing the potential pathogenic effect of such a gene." (PMID 39202774, 2024).
Immunodeficiency (1 paper, 2021). Failure of the immune system to protect the body adequately from infection, due to the absence or insufficiency of some component process or substance. "Interestingly, premature aging and muscle tissue expression disorders were often detected in immunodeficiency mice, and MYH7 and TRIM63 gene expression disorders were also detected." (PMID 33436826, 2021).
infarction (1 paper, 2018). A localised pathological necrosis of tissue resulting from obstruction of the blood supply usually by a thrombus, an embolus, or vascular torsion. "By application of this Cohen’s methodology, we could obtain more reliable data of the two dimensional distribution of the signal intensity on the cardiac tissue and found that MYH7 signal was significantly enhanced in the infarction area." (PMID 29748547, 2018).
kidney damage (1 paper, 2016). "The most linked proteins included Myh6, Myh7, Myh11, Lmna, Des, Tnni3, Mydpc3 and Vcl, revealing that these molecules may be important targets of signaling pathways involved in salt sensitivity in advanced kidney damage." (PMID 27775022, 2016).
myopia (1 paper, 2024). "Because the retina is a neural tissue, the expression of numerous genes linked to cardiac muscle (MYBPC3, ACTC1, MYL3, MYH7, MYH7B) or to skeletal muscle (MYL1, SMYD1, TNNI2, MYH1B, ACTA1, TNNT3) presents a conundrum for explaining a mechanism for myopia progression." (PMID 39028695, 2024).
myositis (1 paper, 2018). "Because both the DBA/2 MYH7 mutation and the equine MYH1 variant are located in the globular head of myosin, it is possible that a mutation in this highly conserved region somehow confers target host susceptibility to myositis." (PMID 29510741, 2018).
prostate carcinoma (1 paper, 2022). A carcinoma that arises from epithelial cells of the prostate gland. "Interestingly, 3 out of 12 novel non-DDR genes (DNMT3A, HMBS and MYH7) were related to DNA methylation that contributes significantly to the development and progression of prostate cancer." (PMID 36095024, 2022).
Right ventricular hypertrophy (1 paper, 2021). In this case the right ventricle is more muscular than normal, causing a characteristic boot-shaped (coeur-en-sabot) appearance as seen on anterior- posterior chest x-rays. "Meanwhile, Cirp‐KO rats showed more aggravated right ventricular hypertrophy with elevated RV/LV + S as well as increased Nppa and Myh7 expression in right ventricle." (PMID 33755319, 2021).
rotator cuff tears (1 paper, 2022). "Some co-expressed mRNAs of LINC01405 (TNNT1 and MYH7) have also been reported in a study of rotator cuff tears." (PMID 36111133, 2022).
Syncope (1 paper, 2022). A transient loss of consciousness (i.e., characterized by a rapid onset, a short duration, and a spontaneous and complete recovery) due to cerebral hypoperfusion. "Two patients (3.7%) had pathogenic and likely pathogenic variants (PV/LPV) in cardiac syncope-related genes TTN and MYH7." (PMID 36005429, 2022).
systemic amyloidosis (1 paper, 2021). "For example, screening for systemic amyloidosis in patients with gelsolin mutation, as well as cardiac and respiratory disease in patients with mutations in MYH7, DMD and LAMA2 genes." (PMID 34103343, 2021).
teratoma (1 paper, 2020). A non-seminomatous germ cell tumor characterized by the presence of various tissues which correspond to the different germinal layers (endoderm, mesoderm, and ectoderm). "However, the area of Myh7 and Myh2a myofibers was significantly lower in Pax7−/− teratomas." (PMID 32552916, 2020).
vacuolar myopathy (1 paper, 2015). "Other vacuolar myopathy related genes previously ruled out in these sporadic patients by Sanger sequencing were: GNE and ANO5 for patient 1s, GNE for 2s, GNE, ANO5 and MYH7 for 3s and GNE for 4s." (PMID 26205529, 2015).
Zinc deficiency (1 paper, 2025). A deficiency of the essential metal Zinc; an essential cofactor for many enzymes. "Two-way ANOVA revealed significant interaction effects between zinc status and Zip10 knockdown for Myh7 and Mb expression (P < 0.05 for both), indicating that the impact of zinc deficiency on these genes depends on ZIP10 expression." (PMID 41347147, 2025).
myopathies (32 papers, 2008 to 2025). "In the present study, WES enabled us to make a possibly diagnosis of myopathy as MSM caused by a mutation in the MYH7 gene." (PMID 37794383, 2023). "This family remarkably widens the genotypic and phenotypic variability of MSM, manifesting the first report of this variant in MYH7-related myopathy with a somewhat distinct phenotype from Iran." (PMID 37794383, 2023). "Other distal mutations in MYH7 were also identified in a myopathy with predominance of small type I fibers." (PMID 35980353, 2022). "Most common are myopathies associated with variants in MYH7, encoding slow/beta cardiac MyHC, which is expressed in type 1 muscle fibers." (PMID 36380287, 2022). "The genetic basis of myosin storage myopathies are mutations in the rod region of MYH7 (slow/b-cardiac myosin heavy chain I) gene, which is mostly expressed in heart muscle and slow type I muscle fibers." (PMID 32456280, 2020). "Myosin heavy chain 7 (MYH7)-related myopathies are caused by mutations in the MYH7 gene, which encodes the β-cardiac myosin heavy chain protein." (PMID 32456280, 2020). "Different phenotypes produced by mutations in TRIM32, even in the same region of the gene, has similarly been reported in other myopathies associated with mutation in other genes such as MYH7." (PMID 30823891, 2019). "Here we report clinical, morphological, and myoimaging data from 21 patients with confirmed mutations in MYH7 to better characterize the emerging genotype–phenotype correlation in these myopathies." (PMID 27387980, 2016). "Recently Lamont and colleagues described well this broadened spectrum of MYH7-related myopathies reporting findings in families with known and novel mutations in MYH7." (PMID 27387980, 2016). "Protein aggregation with features similar to those in myofibrillar myopathy and in the ariel mouse was identified in one patient with a mutation in the rod region of MyHC I (MYH7) mutation." (PMID 22918376, 2013). "Myosin storage myopathy is an additional myopathy associated with mutations in the MYH7 gene." (PMID 19325803, 2008). "Correspondingly, canonical MEF2 target genes linked to myopathy and contractile function, including TNNT2, MYH7, ACTN2, and ACTA1, were also restored upon HDAC5 silencing." (PMID 41283336, 2025). "Our findings broaden the phenotypic spectrum of MYH7-related myopathies and have implications for early diagnosis in affected families." (PMID 35854315, 2022). "The distal nebulin myopathy should be differentiated from other CMs with distal affection, such as those related to MYH7 or ACTA1 mutations, or other muscle diseases with anterior compartment involvement, such as myofibrillar myopathies." (PMID 32456280, 2020). "In fact, no dusty cores were observed among 154 muscle biopsies of dominant RYR1- and 10 of MYH7-related myopathies examined in our lab." (PMID 30611313, 2019). "The pronounced degeneration of anterior tibial muscles observed on MRI showed the main characteristic of MYH7-related myopathies." (PMID 28927399, 2017). "Myosin heavy chain 7 related myopathies are rare disorders characterized by a wide phenotypic spectrum and heterogeneous pathological features." (PMID 27005958, 2016). "Myosin heavy chain 7 (MYH7)-related myopathies are emerging as an important group of muscle diseases of childhood and adulthood, with variable clinical and histopathological expression depending on the type and location of the mutation." (PMID 27387980, 2016). "The levels of MYH6 and MYH7 expression have also been considered as markers for the severity of myopathy." (PMID 25750702, 2015). "Dominant mutations in the MYH7 gene, which encodes the slow/β-cardiac myosin heavy chain (MyHCI) expressed in type 1 muscle fibers and in the heart, are causative of ∼10% of CCD cases, as well as of several other myopathies including MmD and CFTD." (PMID 35980353, 2022).
myopathies (continued). "However, according to the reports from recent years, phenotypic characteristics of myopathies arising from MYH7 gene defects actually have a rather wide spectrum." (PMID 28927399, 2017). "Several previous reports describe familial variability in MYH7-related myopathy." (PMID 27387980, 2016). "There are two reports of recessive form of MYH7 related myopathies." (PMID 27387980, 2016). "Since the RLC gene (MYL2), like MYH7, is expressed in slow skeletal muscle, skeletal muscle biopsies from patients with the Glu22Lys MYL2 mutation exhibited abnormal skeletal muscle histology, similar to patients with ragged red fiber (RRF) myopathy." (PMID 19325803, 2008). "However, apart from the c.4309G>C nucleotide change found in MYH7, none of those variants was located in myopathy-related genes or was common to the affected individuals in family A (data not shown)." (PMID 27519903, 2016). "In the present family with a dominant transmission of core myopathy and distal muscle involvement, MRI clearly documented a preferential involvement of anterior leg muscles orienting toward a diagnosis of LDM and contributing to rank a variant in MYH7 as disease causative." (PMID 27005958, 2016). "However, they are unusual in MYH7 myopathies with late onset." (PMID 27519903, 2016). "Several genes were found to be significantly enriched by simvastatin treatment in primary human muscle cells and were mapped to both OMIM as well as KEGG pathways for myopathy, including DES, TNNT1, MYH7, and DYSF." (PMID 40149400, 2025). "The genes DES, TNNT1, MYH7, and DYSF were identified as important regulatory genes in both the OMIM and KEGG myopathy pathway." (PMID 40149400, 2025). "Other genes have additionally been reported to play important roles in skeletal muscle developments such as MYH2, MYH7 and MYH8 where myosin myopathies involving these genes have been widely reported." (PMID 32315303, 2020). "In these cases, a clinical diagnosis was upheld with possible co-existing MYH7 and CACNA1S-related myopathy." (PMID 29970176, 2018). "Specificity was low considering overall pattern analysis, however, was high for some diseases, such as MYOT, MYH7, GNE-related myopathy, and TTN-HMERF However the low prevalence of these diseases and the limited number of cases may have overestimated these values." (PMID 29997562, 2018).
heart disease (30 papers, 2015 to 2025). "Seven genes were selected for association with heart disease, including five common genes in the MYH7 Q315R variant mice group and one from each of the MYH7Q315R/+ and MYH7Q315R/Q315R groups, and were confirmed by real-time PCR." (PMID 41237118, 2025). "Most MPD-1 mutations are concentrated into a discrete region in the coiled-coil tail, between residues 1600–1700, while mutations in MYH7 that cause heart disease are predominantly found in the motor domain (~ 60%)." (PMID 29660325, 2018). "Inherited cardiomyopathies are a common form of heart disease that are caused by mutations in sarcomeric proteins with beta cardiac myosin (MYH7) being one of the most frequently affected genes." (PMID 28119616, 2016). "In addition, we found several upregulated genes that are implicated in cardiac disease, including bone morphogenetic protein 4 (Bmp4) (LogFC 0.728), α-actin (Acta1) (LogFC 3.335), and myosin heavy chain β (Myh7) (LogFC 1.954)." (PMID 35603785, 2022). "While a few enhancers previously knocked-out in mice have the potential to result in cardiac phenotypes (for example, refs 43, 44), to our knowledge, the Myl2 and Myh7 enhancers are the first examples whose loss has been shown to result in a phenotype consistent with heart disease." (PMID 27703156, 2016). "In this study, the expression of MYH7 was up-regulated in the liver tissues of mice treated with ustilaginoidin D, indicating that mice treated with ustilaginoidin D have a risk of heart disease, and the down-regulation of ITGAV may be closely related to cancer markers." (PMID 40423332, 2025). "We further highlight the necessity for ongoing research into the functional consequences of MYH6 and MYH7 deletions to improve our understanding of their role in the spectrum of cardiac diseases." (PMID 40004541, 2025). "We observed significant upregulation of heart disease markers such as Myh7, Xirp2, and Acta1, indicating the successful establishment of the MI and TAC models." (PMID 39502510, 2024). "Recently, several variants in the sarcomere genes such as Myosin Heavy Chain 7 (MYH7) and Myosin Binding Protein C3 (MYBPC3) have been identified in patients with heart diseases." (PMID 35872890, 2022). "Reactivation of the fetal gene program is a classic indicator of cardiac disease remodeling; hence, expression levels of five commonly measured fetal genes (Acta1, Myh6, Myh7, Nppa and Nppb) were examined via real-time quantitative PCR (qPCR) from LV tissue." (PMID 31899774, 2020). "While the majority of mutations in MYH7, the gene that codes for β-MHC, cause heart disease, about 30 (out of 400) mutations predominantly result in skeletal muscle disease, such as Laing early-onset distal myopathy (MPD-1) and myosin storage myopathy." (PMID 29660325, 2018). "The upregulation of Myh7 and downregulation of Myh6 are common in human heart disease." (PMID 25890300, 2015). "Notably, truncating variants in genes such as TTN, FLNC, DSP, PKP2, and MYH7 were frequently reported, particularly in young decedents with no significant history of cardiac disease." (PMID 41374444, 2025). "Several SFRP4-targeted genes, such as MYH6, MYH7, TNNT2 and NKX2-5, contributed to different types of heart diseases." (PMID 32423033, 2020). "The MYH6/MYH7 ratio is considered as a descriptive indicator of cardiac function, and the shift from MYH6 to MYH7 resulting in a decreased ratio indicated a maladaptive change in cardiac diseases." (PMID 35806390, 2022). "The genes MYH6, MYH7, and MYH12 might have a relationship with the occurrence and development of heart disease, although their regulatory mechanism in OS is unclear.ssGSEA showed that the immune cell infiltration score of high-risk OS patients was significantly lower." (PMID 37031292, 2023).
cancer (17 papers, 2017 to 2025). A tumor composed of atypical neoplastic, often pleomorphic cells that invade other tissues. "Regarding the remaining DEPs, Myh4, Acta1, Tnnt3, Mb, Ttn, Actn2, Myh7, Myl1, Mybpc2, Myl3, and Tnnc2 are associated with several cancers." (PMID 39861068, 2024). "The study also highlights the roles of specific proteins (MYH2, MYL1, MYL2, MYH7) and microRNAs (such as hsa-let-7d-5p) that are the potential biomarkers in cancer progression founded on several analyses." (PMID 39656775, 2024). "We can observe that although MYH1, MYH2, and MYH7 were dysregulated in some of the cancers, their expression levels are very low, except for HNSC." (PMID 37340028, 2023). "Although previous studies in animals highlighted a preferential atrophy of fast fibers in cancer cachexia, we reported in our two preclinical models a decrease in the MYH7 which characterizes slow fibers." (PMID 35406681, 2022). "Nonetheless, exosomal proteins previously reported to be associated with vesicle secretion in cancer cell line supernatants (RAP1A, RAP1B, VAMP1, MYH7, MYO18a, MYOLPF, MYO1E, VPS13B, HSP70) were identified in our samples." (PMID 30764491, 2019). "The scaled estimation (Tumour purity) of 773.555 supports this gene (MYH7) from the methylation aspect to detect promoter level changes in the four cancer types." (PMID 28927463, 2017). "While these observations may dismiss the prognosis utilities of MYLK2, as well as other recurrently perturbed actomyosin genes, e.g., MYH6 and MYH7, the specific functions of these genes still require a detailed functional interrogation in uterine as well as other cancer models." (PMID 33217970, 2020). "Through pan-cancer analysis, we found that MYH1, MYH2, and MYH7 are dysregulated in cancers, including HNSC." (PMID 37340028, 2023).